RNU1-83P (RNA, U1 small nuclear 83, pseudogene)
Gene: Small nuclear RNA gene on chromosome 12 (62,850,738 to 62,850,901, reverse strand). Ensembl gene ENSG00000200296.
Homologues: Orthologues: chimpanzee U1 (99% identical), macaque U1 (93% identical), dog U1 (85% identical), guinea pig U1 (79% identical), guinea pig U1 (76% identical), mouse Gm23249 (73% identical), rat LOC120094948 (71% identical). Paralogues in human: RNU1-1 (92% identical), RNU1-2 (92% identical), RNU1-27P (92% identical), RNU1-28P (92% identical), RNU1-3 (92% identical), RNU1-4 (92% identical), RNVU1-18 (92% identical), RNVU1-29 (92% identical), U1 (92% identical), RNVU1-28 (91% identical), RNVU1-7 (91% identical), RNVU1-31 (91% identical), and 134 more.